LMAN2 (lectin, mannose binding 2)
Description:
Plays a role as an intracellular lectin in the early secretory pathway. Interacts with N-acetyl-D-galactosamine and high-mannose type glycans and may also bind to O-linked glycans. Involved in the transport and sorting of glycoproteins carrying high mannose-type glycans (By similarity).
Synonyms: VIP36; C5orf8; GP36B
Tractability: Antibody: its Gene Ontology location is reachable by antibodies, with high confidence; UniProt predicts a signal peptide or a membrane-spanning region. PROTAC: ubiquitination databases record sites on it; its protein half-life has been measured.
Gene: Protein-coding gene on chromosome 5 (177,315,805 to 177,351,840, reverse strand). Ensembl gene ENSG00000169223.
Subcellular location: Endoplasmic reticulum-Golgi intermediate compartment membrane; Golgi apparatus membrane; Endoplasmic reticulum membrane
Subcellular location (Human Protein Atlas): Golgi apparatus
Pathways (Reactome):
Vesicle-mediated transport: COPII-mediated vesicle transport; Cargo concentration in the ER
Gene Ontology:
Molecular function: carbohydrate binding; D-mannose binding; heat shock protein binding; protein binding
Biological process: positive regulation of phagocytosis; retrograde vesicle-mediated transport, Golgi to endoplasmic reticulum; endoplasmic reticulum to Golgi vesicle-mediated transport
Cellular component: cell surface; endoplasmic reticulum-Golgi intermediate compartment; extracellular exosome; extracellular region; Golgi apparatus; plasma membrane; COPII-coated ER to Golgi transport vesicle; endoplasmic reticulum membrane; Golgi membrane; endoplasmic reticulum-Golgi intermediate compartment membrane; membrane
Genetic constraint (gnomAD): Loss-of-function variants: 22 observed, 41.77 expected, observed/expected ratio (o/e) 0.53, 90% interval 0.38 to 0.75. The upper end of that interval is the gene's LOEUF score, 0.75, which puts it in group 3 of 6, group 1 being the genes least tolerant of losing a copy. Missense variants: 494 observed, 526.45 expected, observed/expected ratio (o/e) 0.94, 90% interval 0.87 to 1.01. Synonymous variants: 207 observed, 218.19 expected, observed/expected ratio (o/e) 0.95, 90% interval 0.85 to 1.07.
Homologues: Orthologues: macaque LMAN2 (99% identical), dog LMAN2 (98% identical), mouse Lman2 (95% identical), guinea pig LMAN2 (94% identical), rat Lman2 (94% identical), pig LMAN2 (94% identical), rabbit LMAN2 (87% identical), chimpanzee LMAN2 (86% identical), tropical clawed frog lman2 (76% identical), zebrafish lman2 (71% identical), Drosophila melanogaster CG5510 (44% identical), Caenorhabditis elegans ile-2 (42% identical). Paralogues in human: LMAN2L (53% identical), LMAN1 (30% identical), LMAN1L (28% identical).
Diseases named in the same sentence as LMAN2 in open-access papers:
LMAN2 is named in the same sentence as 22 diseases in open-access papers, as found by Europe PMC text mining. Sharing a sentence is not in itself a finding about the gene and the disease. The quoted sentences say what the papers report.
breast carcinoma (4 papers, 2022 to 2025). "In conclusion, LMAN2 is expressed in distinct cellular populations, and its expression is positively linked to DNA repair, apoptosis, and metastasis of breast cancer cells and is negatively linked to differentiation and inflammation." (PMID 35707004, 2022). "Our findings suggest that LMAN2, which is expressed at a high level in breast cancer, is linked to an unfavorable prognosis." (PMID 35707004, 2022). "Second, multiple prognostic databases showed that an elevated level of LMAN2 was linked to adverse prognosis among HER2-positive breast cancer patients, and that the elevated level of luminal A type was linked to a good prognosis." (PMID 35707004, 2022). "LMAN2 encodes a type I transmembrane lectin associated with poor prognosis in breast cancer." (PMID 40070009, 2025). "Overall, as a consequence of these findings, LMAN2 expression may be linked to a dismal prognosis among breast cancer patients." (PMID 35707004, 2022). "L-type lectin LMAN2 impedes exosomal release in the exosomal-Golgi pathway and is linked to unfavorable prognosis in HER2+ breast cancer." (PMID 40297587, 2025). "In conclusion, we verified that the LMAN2 mRNA expression is high in diverse tumors using one database and showed substantially elevated LMAN2 expression levels in breast cancer samples using two databases." (PMID 35707004, 2022). "LMAN2 was investigated for its predictive significance in breast cancer utilizing the KM plotter and the bc-GenExMiner v4.7 databases." (PMID 35707004, 2022). "The protein expression of LMAN2 in several subtypes of breast cancer patients as examined with the help of the UALCAN database." (PMID 35707004, 2022). "Multiple databases verified that LMAN2 is expressed at a high level in breast cancer cells, and this expression is linked to an unfavorable clinical prognosis of HER2-positive+ breast cancer." (PMID 35707004, 2022). "The LMAN2 gene map and the expression characteristics of marker genes in breast cancer samples were compared using the Human Cell Landscape database." (PMID 35707004, 2022). "In the future, we plan to verify that LMAN2 is involved in the HR-specific process of DNA damage repair in breast cancer through cell and animal experiments and explore the role that LMAN2 plays in HR." (PMID 35707004, 2022). "In conclusion, LMAN2 expression is positively correlated with resistance to multiple drugs in breast cancer." (PMID 35707004, 2022). "The findings revealed that LMAN2 expression varies depending on the tumor microenvironment of breast cancer." (PMID 35707004, 2022). "Breast cancer patients exhibiting LMAN2 expression have a dismal prognosis, according to the findings from an advanced prognostic model analysis." (PMID 35707004, 2022). "With the use of the GEPIA and UALCAN database systems, we were able to determine the LMAN2 mRNA expression in breast cancer and compare it to that in neighboring normal parental samples." (PMID 35707004, 2022). "The possible function of LMAN2 in breast cancer was investigated in the Human Cell Landscape (HCL) database, Gene Regulatory Network database (GRNdb), and CancerSEA database." (PMID 35707004, 2022). "The drug resistance analysis showed that LMAN2 expression rendered the breast cancer cells resistant to a variety of DNA damage-inducing chemotherapeutic drugs, such as anthracyclines or platinum." (PMID 35707004, 2022). "In this research, we utilized multiple online databases to examine the prognostic impact of LMAN2 and found that the elevated LMAN2 expression is linked to the unsatisfactory prognosis of HER2-positive breast cancer." (PMID 35707004, 2022). "Databases such as the HCL database and CancerSEA were used to further analyze the feature map of LMAN2 and its correlation with the functional status of breast cancer samples at the single-cell level." (PMID 35707004, 2022). "Multiple databases were employed to examine the expression of LMAN2 in breast cancer." (PMID 39618331, 2024).
breast carcinoma (continued). "As expected, greater expression of LMAN2 was detected in breast cancer cells than in MCF‐10A cells." (PMID 39618331, 2024). "Furthermore, the single-cell analysis illustrated that LMAN2 expression had a positive link to breast cancer stemness, proliferation, metastasis, and differentiation." (PMID 35707004, 2022). "Our comprehensive analysis using multiple databases shows that LMAN2 may influence breast cancer patients' prognoses by affecting expression via m6A methylation, and DNA damage repair." (PMID 35707004, 2022). "Meanwhile, we used different datasets to evaluate the possible functions of LMAN2 in breast cancer." (PMID 35707004, 2022). "However, the expression, prognosis, and function of LMAN2 in other tumors are still unclear, especially in breast cancer." (PMID 35707004, 2022). "Nine databases were consulted to evaluate LMAN2 expression and prognosis in breast cancer." (PMID 35707004, 2022). "Therefore, LMAN2 has the potential to be utilized as a treatment target in breast cancer." (PMID 35707004, 2022). "Consequently, the m6A alteration in the LMAN2 gene could provide a promising therapeutic target for treating HER2-positive breast cancer." (PMID 35707004, 2022). "Based on HPA, GOBO, and CCLE databases, the results illustrated that LMAN2 protein was expressed in breast cancer and adjoining normal samples and that a subset of breast cancer cell lines (MDA-MB-157 and MDA-MB-415) had high expression of LMAN2." (PMID 35707004, 2022). "Breast cancer patients exhibited considerably higher LMAN2 mRNA expression levels as opposed to normal samples (p < 0.05)." (PMID 35707004, 2022). "Single-cell analysis and drug resistance analyses combined with DNA damage repair analysis showed that LMAN2 might be involved in HR DNA damage repair, thereby affecting the chemotherapy resistance of HER2 subtype breast cancer, consequently affecting the prognosis." (PMID 35707004, 2022).
COVID-19 (3 papers, 2020 to 2025). A disease caused by infection with severe acute respiratory syndrome coronavirus 2. "For the first time, our study explored the important role of the COVID-19-related epigenetic marker cg04543273 and its associated gene LMAN2 in the COVID-19-related onset and exacerbation of atopic dermatitis." (PMID 39867872, 2025). "Thus, the results from MR supported that cg04543273 and LMAN2 were involved in the association between 10.13039/100020014AD and COVID-19." (PMID 39867872, 2025). "Besides, transcriptome analysis suggested that LMAN2 expression was significantly upregulated among the COVID-19-infected population, and LMAN2 expression was obviously correlated with Type 2 helper cells across different post-infection time points." (PMID 39867872, 2025).
gastric cancer (3 papers, 2014 to 2022). A primary or metastatic malignant neoplasm involving the stomach. "Recently, it was reported that LMAN2 (vesicular integral‐membrane protein VIP36) is overexpressed in gastric cancer." (PMID 32536039, 2020). "LMAN2 is known to be over-expressed in gastric cancer, and we found it was over-expressed in GBM as well." (PMID 24871302, 2014). "LMAN2 is a HUB gene resistant to cisplatin in gastric cancer." (PMID 35707004, 2022).
multiple system atrophy (2 papers, 2020 to 2021). Multiple system atrophy (MSA) is a neurodegenerative disorder characterized by autonomic failure (cardiovascular and/or urinary), parkinsonism, cerebellar impairment and corticospinal signs with a median survival of 6-9 years. "A recent study reported the dysregulation of LMAN2 gene, through DNA methylation changes, in multiple system atrophy, which could be shared with others neurodegenerative diseases." (PMID 33923220, 2021).
allergic disease (1 paper, 2025). An immune response that occurs following re-exposure to an innocuous antigen, and that requires the presence of existing antibodies against that antigen. "integrated multiple large cohorts and found that CpG site cg15344640 in the LMAN2 gene region was significantly associated with the onset of childhood allergic diseases including AD." (PMID 39867872, 2025).
Down syndrome (1 paper, 2020). "In the proximity is also the LMAN2 (Lectin, Mannose-Binding 2) gene, which encodes a type I transmembrane lectin, and is downregulated in humans with Down syndrome." (PMID 33139624, 2020).
lymph node metastasis (1 paper, 2022).
ovarian carcinoma (1 paper, 2022). A malignant neoplasm originating from the surface ovarian epithelium. "LMAN2 is a candidate tumor biomarker for intraperitoneal chemotherapy in the treatment of ovarian cancer." (PMID 35707004, 2022). "Previous studies have shown that LMAN2 is a candidate tumor biomarker in ovarian cancer." (PMID 35707004, 2022).
prostate carcinoma (1 paper, 2023). A carcinoma that arises from epithelial cells of the prostate gland. "In contrast to this study, LMAN2 was upregulated in the urine of prostate cancer patients." (PMID 37371512, 2023).
viral infection (1 paper, 2025). "Meanwhile, LMAN2 was discovered as a potentially vital molecule elucidating the link between viral infection and IMIDs." (PMID 39867872, 2025). "A novel role of LMAN2 was proposed in the relationship between viral infection and AD." (PMID 39867872, 2025).
cancer (7 papers, 2014 to 2024). A tumor composed of atypical neoplastic, often pleomorphic cells that invade other tissues. "Association of LMAN2 expression with clinicopathological characteristics, including clinical stage, race, age, cancer subclasses, histological type, and cancer status..We found high expression of LMAN2 in tissue sections by spatial transcriptomics using SpatialDB." (PMID 35707004, 2022). "The data revealed significantly elevated expression of LMAN2 in the majority of cancer tissue types compared to adjacent normal tissues." (PMID 39618331, 2024). "In this research, we initially used multiple databases to analyze LMAN2 expression in malignant tumors." (PMID 39618331, 2024). "Analysis was conducted with the help of CancerSEA database to compare the correlation of LMAN2 expression in fourteen functional states in different cancers and the correlation of LMAN2 functional states in EXP0052, EXP0054, and EXP0055 single-cell datasets." (PMID 35707004, 2022). "Utilizing the TIMER database, we examined the expression of LMAN2 in tumor samples and nearby normal samples from various kinds of cancer." (PMID 35707004, 2022). "LMAN2 mainly participates in the early secretory pathway and is involved in glycosylation alteration by sorting glycoproteins carrying high mannose-type glycans, which is a general feature of cancer cells." (PMID 24871302, 2014). "Then, the link between the expression level of LMAN2 and drug sensitivity GDSC (Genomics of Drug Sensitivity in Cancer) was analyzed." (PMID 35707004, 2022). "LMAN2 mRNA expression levels were remarkably increased in cancer tissues as opposed to matching normal samples (p < 0.05)." (PMID 35707004, 2022).
tumor (5 papers, 2014 to 2024). "Among the risky genes, CTNNA1, P4HB, and LMAN2 are associated with tumor development." (PMID 24871302, 2014). "The results suggested that LMAN2 knockdown significantly suppressed tumor growth and decreased tumor size and tumor weight compared with those in the sh‐control group, while the MAPK activator inhibited the sensitivity of MCF‐7/DDP cells to DDP induced by LAMN2 knockdown." (PMID 39618331, 2024). "High tumor expression of LMAN2, FZD4, FZD5, or STT3A was associated with no significant PFS increase after IP compared to IV chemotherapy." (PMID 26883286, 2016). "From the previous study of our group, the dysregulated proteins AMBP, KLK3, LMAN2, and TTR were found dysregulated in urine and tumor tissue from PCa patients, while SECTM1 was only found in urine from PCa patients, and CDH1 and EFEMP1 were only in PCa tissue." (PMID 35454907, 2022). "To investigate whether LMAN2 inhibition enhances the chemosensitivity of BC cells to DDP in vivo, we constructed a BALB/c nude mouse subcutaneous tumor model with DDP‐resistant MCF‐7 cells (MCF‐7/DDP)." (PMID 39618331, 2024).
infection (4 papers, 2012 to 2025). The state of being infected such as from the introduction of a foreign agent such as serum, vaccine, antigenic substance or organism. "In the second peak, we observed the correlation of LMAN2 with a greater variety of immune cells, indicating that as a structural protein, its specific role in type 2 inflammation is likely to diminish with prolonged post-infection time." (PMID 39867872, 2025). "The focus of this study on LMAN2's role may be more specific to infection-related AD inflammation." (PMID 39867872, 2025).
neurodegenerative disease (2 papers, 2020 to 2021). A disorder of the central nervous system characterized by gradual and progressive loss of neural tissue and neurologic function. "Our data provide the first evidence for changes in DNA methylation across brain regions in MSA, including in HIP1, LMAN2 and MOBP, all relevant to neurodegenerative diseases." (PMID 31535203, 2020).
kidney disease (1 paper, 2019). "This information combined with prior evidence suggesting that sirtuin (SIRT) proteins are potential therapeutic targets for kidney disease provides a rationale for further studies examining the integration between sirtuin and LMAN2." (PMID 31882861, 2019).
neurological disease (1 paper, 2025). "Ten proteins showed co-localization with a neurological disease using both plasma protein abundance and plasma mRNA abundance (SIRPA, CTSH and CD33 with AD; and ASF1A, FCRL3, VEGFB, TYMP, PVALB, LMAN2 and CD5 with MS)." (PMID 40037332, 2025).
LMAN2 also shares sentences with these, for which no sentence is quoted: atopic dermatitis (1 paper); kidney stone (1); liver diseases (1); lung adenocarcinoma (1); neuroblastoma (1); prion disease (1).